IGLV1-51 (immunoglobulin lambda variable 1-51)
Description:
V region of the variable domain of immunoglobulin light chains that participates in the antigen recognition. Immunoglobulins, also known as antibodies, are membrane-bound or secreted glycoproteins produced by B lymphocytes. In the recognition phase of humoral immunity, the membrane-bound immunoglobulins serve as receptors which, upon binding of a specific antigen, trigger the clonal expansion and differentiation of B lymphocytes into immunoglobulins-secreting plasma cells. Secreted immunoglobulins mediate the effector phase of humoral immunity, which results in the elimination of bound antigens. The antigen binding site is formed by the variable domain of one heavy chain, together with that of its associated light chain. Thus, each immunoglobulin has two antigen binding sites with remarkable affinity for a particular antigen. The variable domains are assembled by a process called V-(D)-J rearrangement and can then be subjected to somatic hypermutations which, after exposure to antigen and selection, allow affinity maturation for a particular antigen.
Synonyms: IGLV151; V1-19
Tractability: Antibody: its Gene Ontology location is reachable by antibodies, with high confidence; UniProt places it where antibodies can reach, with medium confidence; UniProt predicts a signal peptide or a membrane-spanning region.
Gene: Immunoglobulin variable (V) gene on chromosome 22 (22,322,472 to 22,322,969, forward strand). Ensembl gene ENSG00000211644.
Subcellular location: Secreted; Cell membrane
Pathways (Reactome):
Immune System: Antigen activates B Cell Receptor (BCR) leading to generation of second messengers; CD22 mediated BCR regulation; Classical antibody-mediated complement activation; FCERI mediated Ca+2 mobilization; FCERI mediated MAPK activation; FCERI mediated NF-kB activation; FCGR activation; Fc epsilon receptor (FCERI) signaling; Immunoregulatory interactions between a Lymphoid and a non-Lymphoid cell; Initial triggering of complement; Regulation of Complement cascade; Regulation of actin dynamics for phagocytic cup formation; Role of LAT2/NTAL/LAB on calcium mobilization; Role of phospholipids in phagocytosis
Disease: FCGR3A-mediated IL10 synthesis; FCGR3A-mediated phagocytosis; Potential therapeutics for SARS
Hemostasis: Cell surface interactions at the vascular wall
Vesicle-mediated transport: Scavenging of heme from plasma
Gene Ontology:
Molecular function: antigen binding
Biological process: immune response
Cellular component: extracellular exosome; extracellular region; immunoglobulin complex; plasma membrane
Homologues: Paralogues in human: IGLV1-40 (80% identical), IGLV1-47 (79% identical), IGLV1-44 (79% identical), IGLV1-36 (75% identical), IGLV1-50 (74% identical), IGLV2-18 (67% identical), IGLV2-11 (65% identical), IGLV2-8 (64% identical), IGLV6-57 (64% identical), IGLV2-14 (62% identical), IGLV2-23 (62% identical), IGLV3-21 (61% identical), and 81 more.
Diseases named in the same sentence as IGLV1-51 in open-access papers:
IGLV1-51 is named in the same sentence as 1 disease in open-access papers, as found by Europe PMC text mining. Sharing a sentence is not in itself a finding about the gene and the disease. The quoted sentences say what the papers report.
tumour (1 paper, 2021). "Our further research suggested that WAKMAR2 is crucial in regulating the tumour microenvironment and may function by regulating immune-related genes, including IL27RA, RAC2, FABP7, IGLV1-51, IGHA1, and IGHD." (PMID 34321580, 2021).